ARHGEF10L (Rho guanine nucleotide exchange factor 10 like)
Description:
Acts as a guanine nucleotide exchange factor (GEF) for RHOA, RHOB and RHOC.
Synonyms: GRINCHGEF; KIAA1626; FLJ10521
Tractability: PROTAC: ubiquitination databases record sites on it; its protein half-life has been measured.
Gene: Protein-coding gene on chromosome 1 (17,539,368 to 17,697,876, forward strand). Ensembl gene ENSG00000074964.
Subcellular location: Cytoplasm
Subcellular location (Human Protein Atlas): Cytosol; Golgi apparatus; Vesicles
Pathways (Reactome):
Signal Transduction: G alpha (12/13) signalling events; NRAGE signals death through JNK; RHOA GTPase cycle; RHOB GTPase cycle; RHOC GTPase cycle
Gene Ontology:
Molecular function: GTPase activator activity; guanyl-nucleotide exchange factor activity
Biological process: positive regulation of stress fiber assembly; SREBP signaling pathway; actin cytoskeleton organization; regulation of small GTPase mediated signal transduction
Cellular component: cytosol; cytoplasm
Genetic constraint (gnomAD): Loss-of-function variants: 69 observed, 128.87 expected, observed/expected ratio (o/e) 0.54, 90% interval 0.44 to 0.65. The upper end of that interval is the gene's LOEUF score, 0.65, which puts it in group 2 of 6, group 1 being the genes least tolerant of losing a copy. Missense variants: 1,478 observed, 1,690 expected, observed/expected ratio (o/e) 0.87, 90% interval 0.84 to 0.91. Synonymous variants: 710 observed, 699.35 expected, observed/expected ratio (o/e) 1.02, 90% interval 0.95 to 1.08.
Homologues: Orthologues: macaque ARHGEF10L (98% identical), chimpanzee ARHGEF10L (98% identical), dog ARHGEF10L (93% identical), pig ARHGEF10L (93% identical), guinea pig ARHGEF10L (93% identical), rat Arhgef10l (92% identical), mouse Arhgef10l (91% identical), rabbit ARHGEF10L (84% identical), tropical clawed frog arhgef10l (62% identical), zebrafish arhgef10la (53% identical), zebrafish arhgef10lb (49% identical), Drosophila melanogaster CG43658 (22% identical). Paralogues in human: ARHGEF10 (43% identical), ARHGEF17 (23% identical).
Diseases named in the same sentence as ARHGEF10L in open-access papers:
ARHGEF10L is named in the same sentence as 18 diseases in open-access papers, as found by Europe PMC text mining. Sharing a sentence is not in itself a finding about the gene and the disease. The quoted sentences say what the papers report.
Sepsis (3 papers, 2020 to 2024). Sepsis is defined as life-threatening organ dysfunction caused by a dysregulated host response to infection. "The second identified mRNA, encoding ARHGEF10L, was found to be downregulated in sepsis and expression remained low during the ICU stay of septic patients." (PMID 31906585, 2020). "Low expression of ARHGEF10L in CD14 + monocytes is associated with increased death from sepsis, and the list included genes related to anti-bacterial activity (LCN2), regulation of TLR4 responses (SLC15A3), LPS sensitivity and autophagy (RUBCNL and SLC8A1) and apoptosis (FAS, TNFRSF21, TNFRSF8)." (PMID 39730996, 2024). "SIRS-specific biomarkers MPP3, PLA2G7, GPR124 and ARHGEF10L correlated positively with each other and negatively with the sepsis-specific biomarkers and CRP." (PMID 38332914, 2023). "However, these markers correlated well with a prognosis/recovery in the sepsis groups, particularly ARHGEF10L and PLA2G7." (PMID 38332914, 2023). "In contrast, the mRNA encoding for the Rho guanine nucleotide exchange factor (GEF) 10-like protein (ARHGEF10L) decreased in ICU patients compared with healthy controls and was even less abundant in patients with sepsis compared to non-septic patients." (PMID 31906585, 2020).
gastric cancer (2 papers, 2022 to 2024). A primary or metastatic malignant neoplasm involving the stomach. "ARHGEF10L acts through RhoA‐ROCK1‐ERM signal conduction (an essential pathway in tumorigenesis) and stimulates EMT expression in liver and gastric cancer cells." (PMID 38180276, 2024).
hepatocellular carcinoma (2 papers, 2020 to 2021). A malignant tumor that arises from hepatocytes. "We simultaneously demonstrated that increased expression of ARHGEF10L stimulates hepatocellular tumorigenesis by activating the RhoA-ROCK1 (Rho-associated coiled-coil kinase-1)-phospho-ERM (phospho-Ezrin/Radixin/Moesin pathway) and EMT (epithelial-mesenchymal transition) in hepatocellular carcinoma." (PMID 32565805, 2020).
liver cancer (2 papers, 2020 to 2024). An epithelial or non-epithelial malignant neoplasm that arises from the liver. "ARHGEF10L is available to promote liver cancer occurrence, but the mechanism and role of ARHGEF10L in AML have not been reported yet." (PMID 38180276, 2024). "We recently detected a strong association of rs2244444 and rs12732894 in Rho guanine nucleotide exchange factor 10-Like (ARHGEF10L) locus with liver cancer." (PMID 32565805, 2020). "In liver cancer, ARHGEF10L is available to promote tumorigenesis." (PMID 38180276, 2024).
astrocytoma (1 paper, 2017). "Moreover, high expression of 7 of the high-malignant genes (C7ORF46, DUSP4, HS3ST3B1, ODZ1, TTL, VAV3, ZDHHC23) or low expression of 4 of the low-malignant genes (AKR1C3, ARHGEF10L, SMAD7, ST3GAL6) was associated with a lower progression free survival probability of grade III astrocytoma patients." (PMID 29152145, 2017).
cervical (1 paper, 2021). "In this study, we found that the overexpression of ARHGEF10L upregulated the expression of the mesenchymal markers N-cadherin and Slug and downregulated the expression of the epithelial marker E-cadherin, which indicates that ARHGEF10L expression stimulated cervical tumorigenesis by promoting EMT." (PMID 33833821, 2021).
cervical carcinoma (1 paper, 2021). A carcinoma arising from either the exocervical squamous epithelium or the endocervical glandular epithelium. "Our previous study demonstrated a strong association between the ARHGEF10L gene and the risk of cervical carcinoma." (PMID 33833821, 2021). "The HeLa cell line, which was derived from cervical carcinoma, was transfected with ARHGEF10L-overexpressing plasmids or anti-ARHGEF10L siRNA." (PMID 33833821, 2021).
cervical tumors (1 paper, 2021). "The genotyping analysis suggests that the ARHGEF10L gene is also genetically correlated with the risk of cervical tumor risk." (PMID 33833821, 2021). "A Rho pull-down assay and RNA-sequencing analysis were performed to investigate the pathogenic pathway of ARHGEF10L involvement in cervical tumors." (PMID 33833821, 2021). "This study investigated the pathogenic role and mechanism of ARHGEF10L in cervical tumors." (PMID 33833821, 2021). "We determined the role of ARHGEF10L during EMT in cervical tumors." (PMID 33833821, 2021).
gastric tumor (1 paper, 2021). "We investigated the downstream pathway of ARHGEF10L by RNA sequencing analysis in SGC7901 cells that originated from gastric tumors." (PMID 33833821, 2021). "We also found that ARHGEF10L expression stimulated HSPA6 expression in SGC7901 cells that were derived from gastric tumors." (PMID 33833821, 2021). "We reported that ARHGEF10L played a role through RhoA-ROCK1-ERM signaling, an important pathway in tumorigenesis, and stimulated EMT in liver tumors and gastric tumor cells." (PMID 33833821, 2021). "The current study and a study with gastric tumor cells used RNA sequencing to investigate the downstream mechanism of ARHGEF10L and found increased HSPA6 expression in ARHGEF10L-expressing HeLa cells." (PMID 33833821, 2021). "Since we reported that ARHGEF10L played a role through RhoA-ROCK1-ERM signaling, an important pathway in tumorigenesis, and stimulated EMT and HSPA6 expression in liver tumors and gastric tumor cells, we suggest that ARHGEF10L is a novel oncogene in many tumors." (PMID 33833821, 2021).
neuroblastoma (1 paper, 2016). Neuroblastoma (NB) is the most common solid, extracranial childhood tumor. "Additional five mutated genes (LRRC17, PXDN, FZD1, ARHGEF10L, ATRX) were highly expressed in neuroblastoma and involved in cancer progression." (PMID 27009842, 2016). "Other five genes (LRRC17, PXDN, FZD1, ARHGEF10L, ATRX) resulted to be expressed in neuroblastoma and involved in cell migration and invasion." (PMID 27009842, 2016).
ovarian carcinoma (1 paper, 2018). A malignant neoplasm originating from the surface ovarian epithelium. "Recent analyses of a large cohort of Canadian ovarian cancer patients identified variants in ARHGEF10L to be significantly associated with invasive disease and three somatic missense mutations have been identified in ovarian cancer patient samples (COSMIC v86)." (PMID 30261690, 2018).
cancer (3 papers, 2016 to 2024). A tumor composed of atypical neoplastic, often pleomorphic cells that invade other tissues. "Abnormal ARHGEF10L expression appears in various malignant tumors and is also related to Rho‐GTPase activation." (PMID 38180276, 2024). "Since EMT is the primary process involved in cancer invasion and metastasis, we examined the important role of ARHGEF10L in EMT." (PMID 33833821, 2021). "Therefore, we reasonably speculate that ARHGEF10L may be involved in various cancer occurrences through RhoA/Rho kinase signaling pathway." (PMID 38180276, 2024). "ARHGEF10L, belonging to guanine nucleotide exchange factor family, is available to induce GDP/GTP exchange on RhoA,33 and increase in RhoA/Rho kinase signal conduction to promote cancer development and metastasis." (PMID 38180276, 2024).
tumor (3 papers, 2017 to 2023). "We found six heterozygous variants predicted to alter splicing; two in DNA repair-associated genes (BRCA1 and BAP1) and four in tumor suppressor genes (ARHGEF10L, ELL, MYH9, and NCOR2)." (PMID 37234870, 2023). "Recently, we used the Illumina GoldenGate Assay, Sequenom MassARRAY, and TaqMan polymerase to analyze the possible correlations between tag SNPs in the ARHGEF10L locus and various tumor risks." (PMID 33833821, 2021). "Most likely, ARHGEF10L overexpression promoted tumor cell proliferation, migration, and invasiveness to stimulate HSPA6 expression, although the exact function of HSPA6 in tumorigenesis is not well known." (PMID 33833821, 2021). "ARHGEF10L is thus a novel tumor-related gene that plays an important role in tumorigenesis." (PMID 33833821, 2021). "HSPA6 is considered an important tumor-related gene under the control of ARHGEF10L." (PMID 33833821, 2021). "Interestingly, we also observed homozygous deletions affecting its closest paralog ARHGEF10L, suggesting that both genes may be tumour suppressors." (PMID 29089486, 2017).
ARHGEF10L also shares sentences with these, for which no sentence is quoted: acute myeloid leukemia (1 paper); autism spectrum disorder (1); bacterial infection (1); bladder cancer (1); entropion (1).